USP7 (ubiquitin specific peptidase 7)
Diseases named in the same sentence as USP7 in open-access papers (continued):
Sharing a sentence is not in itself a finding about the gene and the disease.
tumor (continued). "Quantifications of IHC data revealed that USP7 overexpression is significantly associated with tumor size (p = 0.0002), cervical node metastasis (p = 0.0002) and clinical stage (p < 0.0001) (median values as cut-off)." (PMID 35931679, 2022). "A particular member of this family, USP7, also known as herpesvirus-associated protease (HAUSP), has drawn significant attention from the research community in recent years due to its important role in the regulation of anti-tumor responses." (PMID 36428632, 2022). "There was a significant reduction in tumor growth and tumor weight after USP7 loss, with tumor volumes inhibited by 64.7% for A375 and 46.4% for B16." (PMID 33869052, 2021). "In vivo tumor formation and gene therapy strategies are necessary to understand the exact molecular mechanism underlying the regulatory role of USP7 on tumor formation and progression." (PMID 32922122, 2020). "It was confirmed that the attenuation of USP7 by another USP7 inhibitor (P20077) inhibits the APC mutated CRC tumor growth in a xenograft model." (PMID 32486158, 2020). "Ubiquitin-specificprotease 7 (USP7) has been implicated in tumor development and metastasis invarious malignancies through the regulation of target protein stability." (PMID 32453339, 2020). "USP7 has also been implicated in the deubiquitination of a number of key proteins involved in tumour suppression, such as PTEN." (PMID 30689917, 2019). "Our current data indicate that USP7 is a potential tumor-specific drug target for APC-mutated CRCs by altering the Wnt signaling pathway." (PMID 29045831, 2017). "Additional in vivo experiments using USP7 floxed mice in combination with an Apc-mutated tumor model will be crucial to confirm the tumor-suppressive effect upon USP7 depletion in the intestine." (PMID 29045831, 2017). "In summary, our findings suggest that USP7 is a promising tumor-specific target for treatment of APC-mutated CRC by targeting pathological Wnt activation." (PMID 29045831, 2017). "USP7 was also implicated to modulate tumor growth and apoptosis in a colon carcinoma xenograft model." (PMID 25605410, 2015). "Univariate analysis revealed that tumor size (≥3 cm, p < 0.001), lymph node metastasis (p < 0.001), advanced tumor stage (p < 0.001), and high USP7 expression (p < 0.001) were associated with OS." (PMID 25519684, 2015). "Additionally, USP7 can also interact with specific immune checkpoint inhibitors and interfere with tumor proliferation due to its high expression in tumor-associated macrophages M2." (PMID 41157055, 2025). "Moreover, most members of the USP family, including USP1 and USP7, participate in the regulation of tumor-associated protein networks by exerting their deubiquitinating functions." (PMID 40672756, 2025). "Indeed, recent evidence has demonstrated that USP7 inhibition can stabilize the IκBα inhibitor, causing the arrest of the NF-κB pathway and restoring tumor cell sensitivity to bortezomib." (PMID 41157055, 2025).
tumor (continued). "Furthermore, gene set enrichment analysis (GSEA) showed that USP7 knockdown is significantly associated with the inhibition of tumor formation by downregulating the genes related to MYC and MAPK3 pathways." (PMID 39840939, 2025). "USP7 has also been implicated in the regulation of anti-tumor immune responses." (PMID 39430244, 2024). "Aberrant expression of USP7 is associated with tumor progression." (PMID 38672118, 2024). "Moreover, we revealed that the combination of USP7 enzymatic inhibitor and afatinib caused a more profound inhibition of tumor progression in vitro and in vivo, partly by suppressing the USP7-HIF2α regulatory axis." (PMID 39406703, 2024). "Through an analysis of proteomic data from ccRCCs and adjacent non-tumor tissues, we herein revealed that Ubiquitin-Specific Peptidase 7 (USP7) was upregulated in tumor tissues, and its depletion by inhibitors or shRNAs caused significant suppression of tumor progression in vitro and in vivo." (PMID 39406703, 2024). "Our findings provide direct evidence that USP7 inhibition may offer a safe and efficacious tumor-specific therapy for both sporadic and germline APC-mutated CRC." (PMID 36669491, 2023). "The results indicate that Usp7 deficiency inhibits tumor progression in Apcmin mice." (PMID 36669491, 2023). "USP7, also known as herpesvirus-associated ubiquitin-specific protease, is involved in modulating the stability of several key proteins, including tumor suppressors, transcription factors, epigenetic modulators, proteins involved in DNA damage response and regulators of immune response." (PMID 36186590, 2022). "USP7 controls the anti-tumor immune response by reprogramming tumor-associated macrophages." (PMID 35884607, 2022). "Regarding this, some studies suggest that increased USP7 expression is associated with a variety of human malignancies, including prostate, breast, lung, cervical, and multiple myeloma cancers, where it regulates the activity of tumor promoter or suppressor proteins." (PMID 37373211, 2023). "Moreover, during anti-tumor immunotherapy, it has been shown that USP7 inhibition causes PD-L1 increased level and IL-10 downregulation by attenuating Treg function, which may contribute to enhancing the therapeutic effect of PD-L1 treatment." (PMID 34869041, 2021). "However, the presence of somatic loss of function (LOF) mutations in T-ALL suggests that USP7 may function as a tumor suppressor gene in T-ALL." (PMID 33664368, 2021). "USP7, as a deubiquitinating enzyme, could regulate the stability of tumor-associated substrates." (PMID 34740372, 2021). "Pharmacological inhibition of USP7 has shown promise in reprogramming the tumor microenvironment, exposing metabolic vulnerabilities, and sensitizing tumors to combination therapies." (PMID 42245660, 2026). "Our findings reveal a novel mechanism through which USP7 senses fructose-2,6-bisphosphate levels to promote PFKM nuclear translocation, thereby sustaining tumor cell survival under nutrient deficiency by activating FAO." (PMID 41818193, 2026). "USP7 promotes immune suppression by stabilizing checkpoint molecules such as PD-L1, modulating FGL1/LAG-3 signaling, reshaping tumor-associated macrophage polarization, and reinforcing T-cell dysfunction." (PMID 42245660, 2026). "Particularly, inhibition of USP7 was shown to reprogram tumor-associated macrophages to M1 macrophages through p38 MAPK pathway activation, thereby enhancing anti-tumor immune responses." (PMID 40247205, 2025).
tumor (continued). "USP7 inhibition decreases PD-1 and PD-L1 interaction and increases the tumor cells’ sensitivity to the action of T cells, which in turn blocks the tumor growth." (PMID 41157055, 2025). "Previous studies on USP7 have focused on its role in regulating tumor survival and progression by stabilizing other key proteins." (PMID 40389405, 2025). "In vivo studies further demonstrated that STS impeded tumor growth, and this inhibitory effect was attenuated by Usp7-OE in tumor cells." (PMID 40365281, 2025). "Elevated levels of USP7 have been shown to facilitate tumor growth by enhancing the immunosuppressive functions of Foxp3+ Tregs." (PMID 40001543, 2025). "Our findings indicated that STS suppressed USP7 expression in Hep-53.4 cells, and the KO of Usp7 in Hep-53.4 cells resulted in inhibited tumor growth, with the inverse also being true." (PMID 40365281, 2025). "In research on mice with Lewis lung carcinoma, inhibiting USP7 led to decreased tumor growth and increased levels of M1 macrophages and CD8+ T cells that expressed IFN-γ." (PMID 40001543, 2025). "USP7 stabilises c-Myc through deubiquitination, enhancing glycolytic flux and supporting tumour growth." (PMID 41463025, 2025). "Taking FT671 as a lead compound, Cheng and collaborators synthesized a series of novel pyrrolo-pyrimidine derivatives and identified YCH2823 as a potent USP7 inhibitor (IC50 = 0.50 μM) with a remarkable anti-proliferative impact on various tumor cells." (PMID 41157055, 2025). "Overall, these results suggested that the abrogation of USP7 can restrict the proliferation of tumor cells in vivo." (PMID 40061891, 2025). "Both in vivo and in vitro proliferation experiments emphasized the central role of DACH1 in USP7-mediated tumor proliferation." (PMID 40389405, 2025). "In tumor cells, USP7 specifically removes ubiquitin moieties from the NF-κB subunit p65, thereby stabilizing p65 and enhancing its transcriptional activity toward pro-inflammatory genes." (PMID 40947005, 2025). "As previously discussed, USP7 plays a key role in tumor development and progression, as well as in the regulation of the immune response." (PMID 41157055, 2025). "Previous research has demonstrated that USP7 plays a protective role in preventing the degradation of PDL1, thereby reducing the susceptibility of tumor cells to T cell-mediated cytotoxicity." (PMID 40365281, 2025). "As anticipated, depending on the substrate and the tumor type, USP7 can act as a tumor suppressor or oncogene." (PMID 41157055, 2025). "In nasopharyngeal carcinoma, USP7 enhances tumor invasiveness and chemotherapy resistance by stabilizing KDM5B." (PMID 40389405, 2025). "USP7 is important in regulating the equilibrium of M1 (which suppresses tumor growth and promotes an anti-tumor immune response) and M2 (which aids in tumor progression and inhibits the immune system) macrophages." (PMID 40001543, 2025). "USP7 acts as an enhancer of the immunosuppressive functions of Treg cells and, at the same time, as a suppressor of Teff cells, promoting the tumor immune evasion response." (PMID 41157055, 2025). "At the same time, abrogation of USP7 decreased the tumor volume and weight in the USP7 KD group compared to the control group, and the difference between these two groups was significant." (PMID 40061891, 2025). "The DUB USP7 is critical for Treg maintenance since inhibition or deletion of USP7 results in decreased FoxP3 protein stability and augmented anti-tumour immunity." (PMID 39929287, 2025). "Studies have found that multiple USP members are closely related to tumor metastasis and proliferation, including ubiquitin-specific protease 7 (USP7)." (PMID 40006058, 2025).
tumor (continued). "Despite USP7 being mainly involved in cell cycle regulation and tumor progression, other biological pathways have been investigated." (PMID 41157055, 2025). "These actions affect different processes, including cellular DNA damage repair, tumor-related signaling pathway regulation, and immune response, indicating USP7 as a promising target for the development of novel antitumor therapeutics." (PMID 41157055, 2025). "P22077, a specific USP7 inhibitor identified through activity-based chemical proteomics, has demonstrated anti-tumor and anti-inflammatory effects." (PMID 40246841, 2025). "Although over twenty USP7 inhibitors have been reported to date, most have been functionally validated only in limited tumour models." (PMID 41463025, 2025). "What's more, Usp7-cKI was witnessed to reduce the antitumor efficacy of Rbpj-cKO, and Rbpj-cKI rescued the tumor reduction phenotype under STS treatment." (PMID 40365281, 2025). "ACSL4, low in EOC, suppresses tumor growth by inducing ferroptosis and M1 macrophage polarization, counteracting USP7-driven antiferroptosis and M1 suppression." (PMID 41280929, 2025). "IHC staining of tumor tissues revealed that USP7 expression was reduced in the shUSP7 and shUSP7+shYY1 groups, but showed no significant change in the shYY1 group." (PMID 38769122, 2024). "In Lewis lung carcinoma models, USP7 inhibitor treatment reduced tumor growth and enhanced M1 macrophage and CD8+ T cell infiltration via the p38 MAPK pathway." (PMID 39678489, 2024). "USP7 promotes cell proliferation, migration, in vitro invasion, and tumor growth by stabilizing TAZ." (PMID 38983924, 2024). "vIRF4 interacts with USP7 specifically through its two derived peptides, vif1 and vif2, which serve as selective USP7 antagonists, leading to the inhibition of its ability to regulate tumor suppression." (PMID 39459858, 2024). "Within tumor inflammation, USP7 modulates tumor growth and immune responses by removing ubiquitin tags from key proteins, thereby altering their stability and function." (PMID 39767641, 2024). "This is not necessarily due to therapy resistance, but rather due to the adaption of USP7 overexpressing tumor cells to genomic instability." (PMID 38672118, 2024). "From a mechanistic perspective, the role of USP7 in tumor inflammation is mainly exerted through its deubiquitinating activity." (PMID 39767641, 2024). "USP7 regulates proteins or genes involved in tumor suppression, DNA damage response, DNA replication, viral infections, and epigenetics." (PMID 38467635, 2024). "USP7 cells formed a very aggressive tumor in our experimental model, with a 100% death rate in saline-treated controls within 34 days." (PMID 38213031, 2024). "Our current understanding of the specific role and mechanism of USP7 in tumor inflammatory responses is relatively limited." (PMID 39767641, 2024). "USP7 inhibitors can reduce the immunosuppressive function of Tregs and thereby enhance the anti-tumor immune response." (PMID 39767641, 2024). "Downregulation of USP7 expression significantly suppressed tumor growth in mice, whereas reduced TRIM21 expression promoted xenograft tumor growth." (PMID 38702792, 2024). "USP7 inhibitors not only hinder the cell proliferation but also reduce PD-L1 levels, thereby boosting the anti-tumor immune response." (PMID 38638430, 2024).
tumor (continued). "Given the potential for USP7 inhibitors to transform “immune desert” tumours into “immune responsive” tumours, this paves the way for a novel therapeutic strategy combining USP7 inhibitors with ICIs." (PMID 38602256, 2024). "Overall, these data indicated that the USP7/KPNB1/YBX1/NLGN3 axis actively regulated tumor progression in GBM." (PMID 38254206, 2024). "In syngeneic models, treatment with USP7 inhibitors led to striking tumor responses resulting in significantly improved survival." (PMID 38602256, 2024). "A related study showed that USP7 is a target for tumor survival and is overexpressed in numerous cancers, leading to extensive research and development efforts focused on drugs targeting USP." (PMID 39748950, 2024). "Employing tissue microarray IHC, we observed upregulation of USP7 in GC tissues relative to para‐tumor tissues." (PMID 38460164, 2024). "Conversely, inhibitors that prevent USP7 from being deubiquitinated can reduce Foxp3+Treg’s ability to suppress the immune system, which can allow tumor cells to evade the immune system." (PMID 38919615, 2024). "USP7 plays a pivotal role in tumor inflammation, with its mechanisms encompassing various facets such as the expression of tumor suppressor genes and the modulation of immune responses." (PMID 39767641, 2024). "USP7, one of the DUBs, has garnered more and more attention on its role in the initiation and advancement of tumours." (PMID 39107958, 2024). "For example, increased USP7 expression in oral squamous cell carcinoma promotes tumor cell proliferation and invasion." (PMID 39767641, 2024). "As the wild-type strain, oZIKV_2k induced tumor remission in 83% (five of six) of treated animals and complete metastatic remission (tumors in the spinal cord) in 33% (two of six) of USP7 tumor-bearing mice." (PMID 38213031, 2024). "After radiotherapy, patients with a USP7 high-expressing tumor had a significantly lower overall survival than patients with a USP7 low-expressing tumor, p = 0.005, comparable to the whole cohort." (PMID 38672118, 2024). "USP7 inhibition promotes anti‐tumour immunity leading to synergy with immune‐checkpoint‐inhibitors, improved tumour efficacy and significant gains in survival benefit." (PMID 38602256, 2024). "USP7 has been shown to foster tumor growth by modifying the immunosuppressive properties of Foxp3 + Treg cells." (PMID 38834869, 2024). "Nevertheless, combining USP8/USP7 inhibitors with PD-1/PD-L1 blockade appears to significantly bolster anti-tumor efficacy." (PMID 38702734, 2024). "Results showed that reducing USP7 expression decreased the metastasis of tumor cells in Zebrafish, while downregulating TRIM21 increased tumor metastasis and reversed the inhibition of metastasis caused by shUSP7 cells." (PMID 38702792, 2024). "We also showed that this negative regulation of DICER by USP7 via MDM2 was relevant to human tumours using cellular and clinical data." (PMID 37867415, 2024). "This article mainly reviews the structure, function, role, and mechanism of USP7 in the tumor inflammation response." (PMID 39767641, 2024). "We also evaluated the effects of USP7 inhibition on tumor growth inhibition in syngeneic models when dosed in combination with immune checkpoint inhibitors (ICIs)." (PMID 38602256, 2024).